CITED2 (Cbp/p300 interacting transactivator with ED-rich tail 2)
Diseases named in the same sentence as CITED2 in open-access papers (continued):
Sharing a sentence is not in itself a finding about the gene and the disease.
diabetes (5 papers, 2016 to 2025). "In summary, we found that stem cell proliferation activity and angiogenesis of hADSCs under diabetes-associated glucolipotoxic conditions were increased in part by modulating the expression of miR-1248 via restraining the expression of CITED2, an inhibitor of HIF-1α." (PMID 32294623, 2020). "Considering these observations, maternal high-fat diet and/or maternal metabolic adverse conditions such as diabetes are likely to interplay with foetal CITED2 expression in human gestation and predispose for CHDs, particularly if the foetuses harbour mutations in the CITED2 gene." (PMID 41295244, 2025). "Our previous study revealed that miR-200b is overexpressed in diabetes-induced NTDs and elucidated the stimulative effect of miR-200b through CITED2 (CBP/p300-interacting transactivator with Glu/Asp-rich C-terminal domain, 2) on neural stem cell apoptosis." (PMID 34930914, 2021). "Simultaneously, the relationship among miR-1248, CITED2, HIF-1α, and diabetes was first reported." (PMID 32294623, 2020). "Disruption of the GCN5-CITED2-PKA signalling module (such as that achieved by CITED2 depletion) also suppressed gluconeogenesis and ameliorated diabetes, suggesting that this module is a promising pharmacological target for treatment of obesity and type 2 diabetes." (PMID 27874008, 2016). "However, diabetes-induced Cited4 expression is unlikely to compensate for the downregulation of Cited2, further indicating that Cited genes have distinct functions." (PMID 41295244, 2025). "Results from a recent study revealed that the miR-1248/CITED2/HIF-1α axis played a significant role in diabetic wound healing, indicating that miR-1248 may be used as a novel therapeutic target for wound healing in patients with diabetes." (PMID 32634115, 2020).
prostate carcinoma (5 papers, 2018 to 2025). A carcinoma that arises from epithelial cells of the prostate gland. "This CITED2-nucleolin axis is associated with prostate cancer metastasis." (PMID 37953273, 2023). "Overexpression of Myb has been detected in both acute myeloid leukemia and non-Hodgkin lymphoma, while Tmem206 and Cited2 overexpression was detected in colon cancer and prostate cancer, respectively." (PMID 35852337, 2022). "We here investigate a role of CBP/p300-interacting transactivator with E/D-rich carboxy-terminal domain-2 (CITED2) in prostate cancer metastasis." (PMID 30291252, 2018). "We also propose that the CITED2–NCL signaling pathway is a potential target for treating prostate cancer metastasis." (PMID 30291252, 2018). "Of six types of cancers evaluated, CITED2 was elevated only in prostate cancer compared with normal tissue." (PMID 30291252, 2018). "In the present study, we found that CITED2 was highly expressed in metastatic prostate cancer because of TMPRSS2–ERG gene fusion, which promoted metastasis by activating NCL at the post-translational level." (PMID 30291252, 2018). "To examine the involvement of CITED2 in prostate cancer progression, we determined CITED2 expression in primary tumor and metastatic tumor tissues and found that CITED2 expression was increased in metastatic tumors." (PMID 30291252, 2018). "ERG and CITED2 overexpression in the TMPRSS2–ERG gene fusion samples further support the ERG-driven overexpression of CITED2 in prostate cancer cells." (PMID 30291252, 2018). "Nonetheless, our cellular and animal experiments support our notion that ERG-induced CITED2 promotes prostate cancer metastasis." (PMID 30291252, 2018). "Because ELK1 in the ETS family has been reported to transactivate the CITED2 gene, we examined which member in the ETS family is responsible for CITED2 gene activation in prostate cancer." (PMID 30291252, 2018). "Informatics and experimental data suggest that the CITED2–nucleolin axis is involved in prostate cancer metastasis." (PMID 30291252, 2018). "In this study, CITED2 was found to be uniquely overexpressed in prostate cancer cells, in which it promoted metastasis by activating the NCL–AKT signaling pathway." (PMID 30291252, 2018). "In particular, CITED2 is suspected to be extensively involved in prostate cancer, since its expression is induced by an ETS family member ELK119, which has been reported to recruit AR to activate growth signaling in prostate cancer cells." (PMID 30291252, 2018). "According to this scenario, CITED2 could be a potential target to prevent prostate cancer metastasis." (PMID 30291252, 2018). "Based on these results, we evaluated whether the CITED2–NCL axis is involved in prostate cancer cell migration." (PMID 30291252, 2018). "Our results suggest that CITED2 plays a metastasis-promoting role in prostate cancer and thus could be a target for preventing prostate cancer metastasis." (PMID 30291252, 2018). "CITED2 expression might correlate with poor prognosis in prostate cancer patients." (PMID 30291252, 2018). "Among genes uniquely downregulated by CBPD-409, we identified NKX3-1, CITED2 and CCND1, which are known for their critical roles in prostate cancer progression." (PMID 41044247, 2025). "Amongst genes uniquely down-regulated by CBPD-409 versus reader bromodomain inhibitors, we identified NKX3–1, CITED2, and CCND1 that are known for their driver roles in prostate cancer progression." (PMID 38586029, 2024). "In this study, we identified a pathway related to metastasis, involving ERG, CITED2, NCL, and AKT pathway, in prostate cancer." (PMID 30291252, 2018). "Here they report CBP/p300-interacting transactivator with E/D-rich carboxy-terminal domain-2 (CITED2) to interact with nucleolin, p300, and PRMT5 subunits, and reveal a role of CITED2-nucleolin axis in prostate cancer metastasis." (PMID 30291252, 2018).
prostate carcinoma (continued). "Immunoblotting analysis in various prostate cancer cell lines showed an apparent correlation between ERG and CITED2 expressions." (PMID 30291252, 2018). "We identified ERG as a transcription factor regulating expression of the CITED2 gene, which is specifically overexpressed in prostate cancer, and further clarified the ERG–CITED2 axis as the downstream pathway involved in prostate cancer." (PMID 30291252, 2018). "Prostate cancer tissues in the GSE6919 data set were divided into low and high expression groups based on the mean CITED2 and NCL expression values." (PMID 30291252, 2018). "We also identified CITED2 and NCL as target molecules for preventing prostate cancer metastasis in an orthotopic xenograft animal model." (PMID 30291252, 2018). "However, CITED2 or NCL expression did not affect cell growth or viability in prostate cancer cells." (PMID 30291252, 2018). "Taken together, these results strongly suggest that the CITED2–NCL axis enhances the metastatic potential, rather than cell growth, in prostate cancer cells." (PMID 30291252, 2018).
breast tumor (4 papers, 2009 to 2025). "CITED-2 regulates/attenuates primary breast tumor growth, likely by influencing tumor vasculature via TGF-beta-dependent regulation of VEGFA." (PMID 39859448, 2025). "Collectively, these data indicate that CITED2 regulates primary breast tumor growth, likely by influencing tumor vasculature via TGF-β-dependent regulation of VEGFA." (PMID 28008154, 2017). "mRNA levels of NCOR2 and CITED2 in oestrogen receptor-positive breast tumours were determined by quantitative RT–PCR." (PMID 19904269, 2009). "While we previously demonstrated that CITED2 expression in primary breast tumor tissues is elevated relative to normal mammary epithelium and inversely correlated with patient survival, its functional impact on primary tumor development and progression remained unknown." (PMID 28008154, 2017). "However, CITED4 (as well as CITED2) have been shown to bind and inactivate HIF-1alpha, and in breast tumors, a negative correlation exists between CITED4 and HIF-1alpha protein expression, which would apparently contradict a role for HIF-alpha regulation of c-MET in the current study." (PMID 26243458, 2016).
acute myeloid leukemia (3 papers, 2017 to 2022). Acute myeloid leukemia (AML) is a group of neoplasms arising from precursor cells committed to the myeloid cell-line differentiation. "Furthermore, adult hematopoietic stem cell (HSC) functions are maintained by CITED2 via lnk4a/Arf and Trp5314, and acute myeloid leukemia critically requires CITED2 expression." (PMID 30291252, 2018). "CITED2 (CBP/p300-interacting-transactivator-with-an-ED-rich-tail 2) is a regulator of the acetyltransferase CBP/p300 and elevated CITED2 levels are shown in a number of acute myeloid leukemia (AML)." (PMID 29072699, 2017).
colon cancer (3 papers, 2009 to 2022). "Loss of CITED2 has been implicated in restored sensitivity to platinum compounds in resistant ovarian cancer cells and in increased invasiveness in a colon cancer model." (PMID 19904269, 2009).
hepatocellular carcinoma (3 papers, 2018 to 2025). A malignant tumor that arises from hepatocytes. "In Hep3B hepatoma cells, upstream stimulatory factor 2 (USF2), a basic helix-loop-helix-leucine-zip transcription factor, cooperates with HIF-2α to promote the hypoxic activation of HIF-2α target genes, including CITED2, EPO, and PAI-139." (PMID 30478339, 2018).
leukemia (3 papers, 2015 to 2019). A malignant (clonal) hematologic disorder, involving hematopoietic stem cells and characterized by the presence of primitive or atypical myeloid or lymphoid cells in the bone marrow and the blood. "In order to demonstrate that CITED2 truly impacts the survival and maintenance of leukemia initiating cells (LICs, or LSCs), AML cells were transduced with a lentiviral GFP-vector expressing a short hairpin targeting CITED2 (shCITED2) or a control vector." (PMID 29072699, 2017). "Human hematopoietic stem cell maintenance mediated by the transcriptional coactivator CITED2 contributes to leukemia maintenance." (PMID 25915206, 2015).
lymphoma (3 papers, 2014 to 2022). A malignant (clonal) proliferation of B- lymphocytes or T- lymphocytes which involves the lymph nodes, bone marrow and/or extranodal sites. "Both Tmem206 and Cited2 were recently described as oncogenes involved in lymphoma in human cells." (PMID 35852337, 2022). "CITED2, a transcription modulator essential for glycolytic metabolism for adult hematopoietic stem cells and potential tumor suppressor, was found deleted in 2 cases of lymphoma by CNV analysis in frozen tissues." (PMID 24699316, 2014).
Obesity (3 papers, 2016 to 2023). Accumulation of substantial excess body fat. "In this context, our findings show that myeloid-CITED2 deficiency exacerbates HFD-induced obesity, subcutaneous and visceral fat accumulation, glucose intolerance, and insulin resistance in vivo." (PMID 37681868, 2023). "Butyrate can regulate the expression of Cited2, which associates with obesity by inhibiting the HDAC." (PMID 35458198, 2022). "Thus, we hypothesized that macrophage-CITED2 deficiency will augment HFD-induced obesity and insulin resistance in vivo." (PMID 37681868, 2023). "In this study, our analyses show that myeloid-CITED2 deficiency promotes HFD-induced adipose tissue inflammation, adverse remodeling of adipocytes, expansion of adipose tissue volume, obesity, insulin resistance, and glucose intolerance." (PMID 37681868, 2023). "Our in vivo studies show that myeloid-CITED2 deficiency significantly elevates high-fat diet (HFD)-induced expansion of adipose tissue volume, obesity, glucose intolerance, and insulin resistance." (PMID 37681868, 2023). "Overall, these findings show that myeloid-CITED2 knockdown significantly exacerbates HFD-induced obesity and insulin resistance." (PMID 37681868, 2023). "Overall, our findings highlight that CITED2 restrains inflammation by promoting BCL6 expression in macrophages, and limits diet-induced obesity and insulin resistance." (PMID 37681868, 2023). "Collectively, our analyses uncover the pleiotropic nature of CITED2 which attenuates inflammation by promoting BCL6 expression in macrophages, and substantially curbs diet-induced obesity and insulin resistance in vivo." (PMID 37681868, 2023). "Herein, we provide evidence that myeloid-CITED2 limits pro-inflammatory gene expression by elevating BCL6 signaling, and substantially curtails diet-induced obesity and insulin resistance." (PMID 37681868, 2023). "Despite previous studies indicating a role for hepatic-CITED2 in gluconeogenesis, the importance of myeloid-CITED2 signaling in diet-induced obesity and insulin resistance has not been investigated." (PMID 37681868, 2023). "In this study, we found that myeloid Cbp/p300-interacting transactivator with Glu/Asp-rich carboxy-terminal domain 2 (CITED2) promotes BCL6 signaling to limit the expression of inflammatory gene targets and the pathogenesis of diet-induced obesity and metabolic dysfunction." (PMID 37681868, 2023). "However, whether myeloid-CITED2 plays any significant role in the pathogenesis of diet-induced obesity and insulin resistance has not been examined." (PMID 37681868, 2023).
ovarian carcinoma (3 papers, 2009 to 2023). A malignant neoplasm originating from the surface ovarian epithelium. "Further analysis showed that ovarian cancer patients with high level of CITED2, LYVE1, OGN, RAP1A, and TBC1D22A had a poor prognosis that that with level of CITED2, LYVE1, OGN, RAP1A, and TBC1D22A (all p < 0.05)." (PMID 37784081, 2023). "The protein level of CITED2, LYVE1, OGN, RAP1A, and TBC1D22A were higher in ovarian cancer tissues than that in normal tissues." (PMID 37784081, 2023). "In ovarian cancer cells, increased TSG101 levels upregulate CBP/p300-interacting transactivator with ED-rich tail 2 (CITED2) and hypoxia-inducible factor 1α (HIF-1α), while downregulating tumor suppressor p21 and subsequently promoting cell growth and survival." (PMID 30759747, 2019).
ventricular septal defect (3 papers, 2014 to 2022). The presence of a defect (opening) in the septum that separates the two ventricles of the heart. "Variants in the coding region of the CITED2 gene lead to a range of cardiac malformations and congenital heart defects, such as ventricular septal defect (VSD), ASD, and tetralogy of Fallot (TOF)." (PMID 36286273, 2022). "Heterozygosity for the left right patterning gene Cited2 reduces but does not eliminate Pitx2c expression and is associated with a partially penetrant phenotype of ventricular septal defect and double outlet right ventricle." (PMID 29755990, 2014).
atherosclerosis (2 papers, 2024). A disease characterized by the build-up of fatty material and calcium deposition in the arterial wall resulting in partial or complete occlusion of the arterial lumen. "The contributions of CITED2 to macrophage polarization and its role in a variety of inflammatory disorders, including atherosclerosis and diet-induced obesity, has been well explored using mouse models and primary cells." (PMID 38646545, 2024).
colorectal cancer (2 papers, 2021 to 2025). A primary or metastatic malignant neoplasm that affects the colon or rectum. "CITED2 gene silencing modulated adherens/tight junction gene expression and reduced cell proliferation in SW480 colorectal cancer cell line." (PMID 39907030, 2025).
endometriosis (2 papers, 2020 to 2024). The growth of functional endometrial tissue in anatomic sites outside the uterine body. "Interestingly, endometriosis-associated gene dysregulation in early secretory phase matches dysregulation in the transgenic mouse endometrium in the present study in terms of affected gene-set, above all the progesterone-regulated genes (e.g. Errfi1, Bcl6, Cited2, Irs2, Tgfb2, Gpx3, Tk1)." (PMID 38346980, 2024).
Insulin resistance (2 papers, 2023 to 2025). Increased resistance towards insulin, that is, diminished effectiveness of insulin in reducing blood glucose levels. "To explore the impact of myeloid-CITED2 deficiency on HFD-induced insulin resistance, we performed glucose and insulin tolerance tests (GTT and ITT) by utilizing Lyz2cre and Cited2fl/fl:Lyz2cre mice." (PMID 37681868, 2023).
lung carcinoma (2 papers, 2018 to 2021). "It has been reported that CITED2 promotes MYC-mediated transactivation of the E2F3 gene by recruiting p300 to stimulate lung cancer progression." (PMID 30291252, 2018). "We examined CITED2 expression in 28 different types of cancer using The Cancer Genome Atlas (TCGA) database and found relatively high CITED2 mRNA levels in thyroid, kidney, ovarian, lung, prostate, breast, and lung cancers." (PMID 30291252, 2018).
metastatic prostate carcinoma (2 papers, 2018 to 2025). A carcinoma that arises from the prostate gland and has spread to other anatomic sites. "We thus conducted a screening in patients to identify the cancer type most affected by CITED2 expression and found that CITED2 was most elevated in metastatic prostate cancer." (PMID 30291252, 2018). "CITED2 is highly expressed in metastatic prostate cancer, and its expression is correlated with poor survival." (PMID 30291252, 2018). "We therefore propose that CITED2 may be a potential target for treating metastatic prostate cancer." (PMID 30291252, 2018).
pancreatic cancer (2 papers, 2022 to 2025). "Furthermore, the qPCR results indicated the mRNA expression levels of JMJD6, ANKZF1, CITED2, and ENO3 was obviously decreased in pancreatic cancer cells versus the normal pancreatic ductal epithelial cells, whereas those of LDHA, TES, and SIAH2 were oppisite." (PMID 35935823, 2022).
rhabdomyosarcoma (2 papers, 2025). A rare aggressive malignant mesenchymal neoplasm arising from skeletal muscle. "Spindle cell/sclerosing rhabdomyosarcomas typically harbor certain genomic alterations, including rearrangements involving TFCP2, VGLL2, NCOA2, CITED2, TEAD1, and SRF, as well as the MYOD1 p.L122R mutation." (PMID 40361368, 2025).
Stroke (2 papers, 2022 to 2023). Sudden impairment of blood flow to a part of the brain due to occlusion or rupture of an artery to the brain. "E2F family members (E2F1 and E2F4) are involved in the regulation of CITED2 expression in neurons after stroke-related injury." (PMID 36358994, 2022). "E2F1/4 is involved in the regulation of CITED2 expression in neurons after stroke-related injury." (PMID 38003393, 2023).
thyroid cancer (2 papers, 2021 to 2022). "For example, a previous study found that inhibiting GINS2 expression promotes apoptosis of thyroid cancer cells by mediating the down-regulation of downstream proteins CITED2 and LOXL2." (PMID 36092720, 2022). "GINS2 promotes cell proliferation and inhibits cell apoptosis by regulating CITED2 and LOXL2 in thyroid cancer." (PMID 34288816, 2021).
ventricular septal defect 2 (2 papers, 2020 to 2022). Any ventricular septal defect in which the cause of the disease is a mutation in the CITED2 gene. "Deleterious mutations in CITED2 cause ventricular septal defect 2 (VSD2)." (PMID 32475352, 2020).
anemia (1 paper, 2021). A reduction in the number of red blood cells, the amount of hemoglobin, and/or the volume of packed red blood cells. "Taken together, while Cited2 deletion compromises erythroid progenitors and causes mild anemia, it is otherwise not essential for normal steady-state multilineage hematopoiesis in young adult mice." (PMID 34715054, 2021). "Notably, consistent with mild anemia, mice lacking Cited2 had significantly decreased numbers of BM erythroid progenitors." (PMID 34715054, 2021).
Anxiety (1 paper, 2023). Intense feelings of nervousness, tension, or panic often arise in response to interpersonal stresses. "An in vivo infusion of an antagomir against miR-494 into the amygdala’s central nucleus was able to mimic the anti-anxiety behavioral effects of ethanol and increase the expression of CBP/p300-interacting transactivator 2 (Cited2), CREB binding protein (CBP) and p300." (PMID 36979479, 2023).